NPR1 (natriuretic peptide receptor 1)
Diseases named in the same sentence as NPR1 in open-access papers (continued):
Sharing a sentence is not in itself a finding about the gene and the disease.
skin cancer (2 papers, 2013 to 2014). "Interestingly, other recent studies have highlighted the importance of autocrine VEGF/NPR1 signalling in the initiation of skin tumours and glioblastomas." (PMID 23436775, 2013).
Arterial thrombosis (1 paper, 2024). The formation of a blood clot inside an artery. "Moreover, guanylate cyclase (NPR1) was associated with clopidogrel, a crucial therapeutic agent for antiplatelet control of arterial thrombosis in cats, and beta-blocker agents (propranolol and atenolol) for controlling heart rate and reducing blood pressure." (PMID 38970022, 2024).
cardiomyopathies (1 paper, 2019). "Interestingly two brothers with hypertrophic cardiomyopathy have a novel missense variation in NPR1, the gene encoding the natriuretic peptides receptor type I, not reported previously to be causing cardiomyopathies." (PMID 30764827, 2019).
chordoma (1 paper, 2017). Chordomas are rare malignant tumors arising from embryonic remnants of the notochord in axial skeleton. "ULK4, NPR1 and CDKL4 were the top most expressed kinases in the Chor-IN-1 cell line, while FGFR3, KDR and WNK2 were less expressed or absent in Chor-IN-1 cells as compared to the other chordoma lines." (PMID 28835717, 2017).
COVID-19 (1 paper, 2022). A disease caused by infection with severe acute respiratory syndrome coronavirus 2. "SARS-CoV-2 was found in Neuropilin-1 (NRP-1) -positive OSNs of the OE, OB and olfactory tracts in COVID-19 patients, indicating the critical roles of NPR1 in virus entry of the OSNs and anosmia." (PMID 35759516, 2022).
Dry skin (1 paper, 2021). Skin characterized by the lack of natural or normal moisture. "The normal dry skin itch in Npr1 KO mice prompted us to examine Nppb expression in DRGs of dry skin mice." (PMID 34919054, 2021).
fibrosis (1 paper, 2022). the formation of excess fibrous connective tissue in an organ or tissue in a reparative or reactive process. "In order to reveal the mechanisms whereby Npr1 gene disruption induces cardiac fibrosis, we first attempted to determine the mRNA expression of the fibrotic markers in heart tissues of Npr1−/− mice by qRT-PCR." (PMID 36232788, 2022). "The global ablation model of Npr1 in mice provided a broad support for the studies of the pathophysiology of cardiac fibrosis, hypertrophy, and remodeling in disease states." (PMID 36232788, 2022). "The results of the current study demonstrate that the disruption of Npr1 induces cardiac fibrosis through the TGF-β1/SMAD-dependent pathway by enhancing the expression of SMAD proteins involved in the canonical cascade." (PMID 36232788, 2022). "The results demonstrate that the blockade of TGF-β1/SMAD signaling with the new generation TGF-β1 receptor (TGF-β1R) antagonist, GW788388, dramatically inhibited the cardiac fibrosis and dysfunction in Npr1 mutant animals." (PMID 36232788, 2022). "Thus, the targeted canonical TGF-β1 signaling cascade might play a central role in the maladaptive cardiac fibrosis and dysfunction in Npr1−/− mutant mice." (PMID 36232788, 2022).
Glucose intolerance (1 paper, 2024). Glucose intolerance (GI) can be defined as dysglycemia that comprises both prediabetes and diabetes. "Npr1+/− mice developed a moderate glucose intolerance despite unchanged insulin sensitivity under SD." (PMID 39383215, 2024).
microsporidia infection (1 paper, 2015). "Thus, the npr-1 gene does not appear to be responsible for the enhanced resistance to microsporidia infection of HW animals compared to N2 animals." (PMID 25680197, 2015).
ovarian tumours (1 paper, 2020). "NPR1 protein expression was increased in gastric, lung, skin, and ovarian tumours." (PMID 32452127, 2020).
pituitary tumour (1 paper, 2021). "Furthermore, our data suggest enhanced expression of NPR1 in feline pituitary tumour samples compared with normal feline pituitary tissue, which might indicate a potential regulatory role for ANP/NPR1 signalling in feline pituitary function." (PMID 33499110, 2021).
preeclampsia (1 paper, 2023). Preeclampsia is a hypertensive disorder of pregnancy that is characterized by new-onset hypertension with proteinuria presenting after 20 weeks of gestation, and depending on mild or severe forms may initially present with severe headache, visual disturbances, and hyperreflexia. "The immunoreactivity of NPR1 should also be considered in the context of preeclampsia and warrants further investigation." (PMID 37047162, 2023). "Here, the mRNA expression of NPR1, one of three natriuretic receptors and the principal receptor of ANP, was significantly upregulated in omental arteries from women with preterm preeclampsia compared to normotensive controls." (PMID 37047162, 2023).
Renal insufficiency (1 paper, 2024). A reduction in the level of performance of the kidneys in areas of function comprising the concentration of urine, removal of wastes, the maintenance of electrolyte balance, homeostasis of blood pressure, and calcium metabolism. "Significant increases in plasma creatinine concentrations and decreased CrCl rates suggest the onset of renal insufficiency with podocyte-specific disruption of Npr1." (PMID 39101921, 2024).
rubella (1 paper, 2015). A viral infection caused by the rubella virus. "To gain insights into the evolutionary history of the incompatible alleles, we sequenced an ∼700-bp fragment surrounding the 39-nt deletion in NPR1 from 10 grandiflora, 18 rubella and 10 orientalis accessions." (PMID 26268845, 2015).
ulcerative colitis (1 paper, 2022). An inflammatory bowel disease involving the mucosal surface of the large intestine and rectum. "A very recent study has reported that decreased levels of ANP and NPR1 exacerbate ulcerative colitis in humans and the experimental mice." (PMID 35794311, 2022).
infection (210 papers, 2009 to 2026). The state of being infected such as from the introduction of a foreign agent such as serum, vaccine, antigenic substance or organism. "Upon pathogen infection, the induction of SA causes the oligomeric NPR1 to dissociate into monomers, and the bacterial type III effector AvrPtoB directly targets NPR1 and mediates the degradation of NPR1 through the 26 S proteasome to disrupt plant immunity." (PMID 37230965, 2023). "Results showed that the infection of TuMV caused an evident increase in the level of NPR1 sumoylation and phosphorylation modifications, indicating that TuMV infection stimulates the SA-NPR1 signaling pathway." (PMID 37328517, 2023). "Mutation of NPR1 or ICS1/SID2 strongly decreased PR1 transcription more than that of ALD1 during PsmES4326 infection (OD600 = 0.01)." (PMID 36523630, 2022). "Pathogen infection causes accumulation of SA thus leads to post-translational modification of NPR1, allowing it to enter into the nucleus." (PMID 34829975, 2021). "During pathogenic infection or SA treatment, the NPR1 oligomer in the cytoplasm disintegrates into its monomeric form, which translocates into the nucleus to interact with several TGA family members, and subsequently induces the transcription of PR genes." (PMID 33042179, 2020). "It suggests that infection of P. litchii stimulate the resistant action by up-regulated NPR1 and PP2Cs at early stage of incubation phase in susceptible cultivar." (PMID 30808947, 2019). "In infected plants, a high concentration of SA induces NPR3 and NPR1 interaction, which leads to turnover of NPR1 and defense-associated programmed cell death at the site of infection (local part)." (PMID 30720746, 2019). "At a low infection dosage all three mutants exhibited resistance responses, whereas control npr1 mutants showed the expected disease susceptible phenotype." (PMID 30458055, 2018). "(c) At the site of pathogen attack, high SA levels active NPR3‐directed NPR1 destruction, thereby lifting NPR1‐repression of HR causing cell death at the infection site." (PMID 31245748, 2018). "Results indicated that the presence of a functionally active NPR1 reduced the plant’s susceptibility to the infection, with about 99% of variability in Pseudomonas spore growth between npr1 mutant and wild-type samples." (PMID 29169324, 2017). "It is possible that the down-regulation of defense genes such as NPR1 attributed to the susceptibility of black pepper to the infection of P. capsici." (PMID 27313593, 2016). "Blocking NPR1 degradation pharmacologically with proteasome inhibitors or genetically by mutation of Cullin 3 resulted in accumulation of NPR1 monomer, moderate induction of NPR1 target genes, and elevated resistance to pathogen infection." (PMID 25821454, 2015). "Arabidopsis thaliana (Arabidopsis) npr1 mutants exhibit higher susceptibility to pathogen infection and impaired expression of PR genes." (PMID 24314063, 2013). "It is able to partially complement the Arabidopsis npr1-2 mutation in transgenic Arabidopsis plants in a leaf infection assay and translocate into nucleus upon SA induction in the same manner as the endogenous Arabidopsis NPR1 protein." (PMID 21078185, 2010). "To functionally define the TcNPR1 gene, we transferred TcNPR1 into an Arabidopsis npr1 mutant that is highly susceptible to infection by the plant pathogen Pseudomonas syringae pv." (PMID 21078185, 2010). "Driven by the constitutive CaMV35S promoter, the cacao TcNPR1 gene partially complemented the npr1 mutation in transgenic Arabidopsis plants, resulting in 100 fold less bacterial growth in a leaf infection assay." (PMID 21078185, 2010). "Further, GmNPR1-complemented npr1-1 plants were able to show induction of SAR following infection with an avirulent pathogenic strain." (PMID 19656407, 2009).
infection (continued). "Either following pathogenic infection or in response to SA treatment, NPR1 oligomer becomes monomer and moves into the nucleus to activate transcription of pathogenesis-related (PR) genes." (PMID 19656407, 2009). "During the early and mid-infection stages, the high expression of NPR1 (CCA0526S0240) may be associated with early pathogen recognition and rapid stress response." (PMID 40094748, 2025). "In the mid-to-late stages of infection, NPR1 (CCA0526S0239) is up-regulated, which may be associated with systemic acquired resistance (SAR)." (PMID 40094748, 2025). "NPR1-knockout or NPR1-knockdown plants, SA biogenesis-deficient mutants, and transgenic plants expressing a salicylate hydroxylase gene (NahG) all show enhanced susceptibility to infection by adapted viruses." (PMID 37328517, 2023). "NPR1-mediated SINC formation may be essential for robust transcriptional reprogramming to redirect energy for defense instead of growth upon pathogenic infection." (PMID 35154230, 2022). "Based on this knowledge, it seemed possible that additional mutation of ALD1 in npr1 or sid2 mutant background could weaken early defense against PsmES4326/AvrRpt2 infection." (PMID 36523630, 2022). "Furthermore, EDS1 stabilizes NPR1 protein level, while NPR1 sustains EDS1 expression during pathogenic infection." (PMID 35154230, 2022). "Likewise, the challenging of chilli plants with B. amyloliquefaciens CRN9 suppressed the infection of GBNV in chilli due to the induction of genes NPR1, PAL, PO, SAR8.2, PDF, LOX, EAS1, and WRKY33 associated with ISR/SAR pathway." (PMID 34946111, 2021). "Similarly, nuclear NPR1 levels were lower at the infection site of an avirulent pathogen causing cell death by NPR3/4-mediated degradation." (PMID 34911942, 2021). "In uninduced conditions, a small quantity of NPR1 is constitutively localized in the nucleus and is subjected to proteasomal degradation to avoid unnecessary defense gene activation, whereas pathogenic infection or salicylic acid induction promotes NPR1 monomerization and nuclear translocation." (PMID 32781507, 2020). "In addition, npr-1 mutants exhibit a deficient immune response to pathogens, which plays a key role in enhancing their susceptibility to infections." (PMID 28179390, 2017). "Similarly, enhanced bacterial biomass could be detected in npr1 plants in all assays in accordance to earlier publications demonstrating enhanced susceptibility of npr1 plants towards infection of Pst DC3000 and Psm." (PMID 27895701, 2016). "This study provides a mechanistic framework for understanding NPR1-mediated tolerance to CLas during the initial stages of infection." (PMID 41626336, 2026). "Based on the results from pathogen infection experiments with Xoo and M. oryzae, we analyzed the expression of key defense-related genes (PR1a, PR5, NPR1) to investigate the molecular basis of increased susceptibility in the KO lines." (PMID 40650151, 2025). "The expression of key defense-related genes (PR1a, PR5, and NPR1) was reduced by 61.8–68.3% in KO lines relative to WT upon pathogen infection, indicating that OsbZIP76 positively regulates PR gene induction during immune activation." (PMID 40650151, 2025). "As SA levels rise during pathogen infection, its binding to NPR3/NPR4 releases transcriptional repression of defense genes during pathogen infection, whereas the binding of SA to NPR1 further activates the expression of defense genes." (PMID 40343347, 2025). "Overexpression of NPR1 genes in various plant species reduces ROS levels and enhances ROS scavenging activity during pathogen infection." (PMID 41118530, 2025). "Previously, we found that NPR1 plays a critical role in restricting the compatible infection by TuMV." (PMID 39981868, 2025). "After infection, SA levels increase in the plant, enhancing NPR1 degradation, allowing its monomeric form to migrate to the nucleus and interact with TGA proteins to boost SA-mediated PR gene expression." (PMID 40050684, 2025).
infection (continued). "Our evidence shows that ATG6 interacts with NPR1 and works together to counteract pathogen infection by positively regulating NPR1 and SA levels in vivo." (PMID 40036061, 2025). "NPR1 likely maintains immune homeostasis through feedback inhibition of SA biosynthesis, preventing excessive SA accumulation upon infection, thereby suppressing the over-induction of callose and ROS biosynthesis-related genes." (PMID 41118530, 2025). "Most of the SA-responsive genes of ugt76b1 show SID2 and NPR1 dependence based on the responsiveness of npr1 and sid2 to pathogen infections." (PMID 38780624, 2024). "In recent years, NPR1, as a regulatory protein, has been found to be required in the development of inducible resistance induced by pathogen infection." (PMID 39684810, 2024). "We recently demonstrated that ASM limits the extent of infection of an RNA virus, plantago asiatica mosaic virus (PlAMV), in Arabidopsis in an NPR1-dependent manner." (PMID 38339085, 2024). "Consistent with transcriptome and proteome data, the transcription levels of NPR1 were similar between COM and cgb both before and after Psm ES4326 infection, whereas the NPR1 protein level was much higher in COM than that in cgb after Psm ES4326 infection." (PMID 38284752, 2024). "SAR is an inducible plant defense mechanism that provides broad-spectrum immunity against secondary infections in plant tissues beyond the initial infection site, with NPR1 serving as a crucial regulator." (PMID 39161600, 2024). "The most common response downstream of NPR1 is the accumulation of pathogenesis-related proteins (PRs), which are collectively induced upon infection." (PMID 37620815, 2023). "The response to Pst DC3000 infection varied among the WT mock, WT primed, npr1-1 mock, and npr1-1 primed groups." (PMID 37299116, 2023). "These intermediate levels of SA would be high enough to disrupt the interaction of NPR1 with NPR4 but too low to promote NPR3-associated degradation, leaving the cells in a primed state for rapid response to infection." (PMID 37620815, 2023). "In general, temporary increases in expression were observed for ICS1, EDS1, and NPR1 following G5H infection on ‘L29’ plants." (PMID 37099452, 2023). "Prior to pathogen infection, the SA concentration is low, and NPR1 is inactivated through disulfide bonds." (PMID 38003355, 2023). "Following infection by fungal pathogens such as Magnaporthe oryzae, the SA signaling regulator, NPR1 sequesters bHLH in the cytosol, which activates SA signaling but represses JA signaling." (PMID 37104505, 2023). "Notablt, during pathogen infection, GSTU19—a member of the GST family—is detected within NPR1-associated complexes, implying potential degradation." (PMID 37765358, 2023). "Plants primed through SAR equip themselves with pattern recognition receptors and pathogen-responsive MPKs which are then activated upon a second infection by elicitors such as the flagellin-derived peptide flg22 and depend on NPR1." (PMID 37223806, 2023). "Three redox-sensitive IDRs punctuated with cysteines in NPR1 upon infection and in the presence of SA mediate NPR1 condensation in the cytoplasm forming the so-called SA-induced NPR1 condensates (SINCs)." (PMID 36516452, 2023). "SA induces the formation of monomers of NPR1 from oligomers; SA-bound NPR1 enter into the nucleus to control the production of downstream resistance proteins, such as PRs induced by pathogens in infection." (PMID 37958694, 2023). "The transcript expression of NPR1 showed a ~0.6-fold increase in the Col-0 and a significant reduction of ~2-fold in the gi-100 plant samples with infection." (PMID 36968378, 2023). "Prior to pathogen infection, NPR1 is localized in the cytosol and characterized by covalent disulfide-bridged oligomers." (PMID 35207610, 2022). "Upon infection, NPR1 is reduced to monomeric and translocated into the nucleus where it activates plant immune responses." (PMID 35207610, 2022).